CFAP97D2 (CFAP97 domain containing 2)
Gene: Protein-coding gene on chromosome 13 (114,154,691 to 114,223,085, forward strand). Ensembl gene ENSG00000283361.
Homologues: Orthologues: chimpanzee CFAP97D2 (96% identical).